PHF8 (PHD finger protein 8)
Diseases named in the same sentence as PHF8 in open-access papers (continued):
Sharing a sentence is not in itself a finding about the gene and the disease.
tumor (continued). "Although PHF8 knockout did not affect primary tumor growth or tumor mass at termination of the experiment (40 days), it led to a significant decrease in lung metastasis burden measured by ex vivo bioluminescence, which corresponded to a reduced number of metastatic foci." (PMID 35179962, 2022). "Finally, we injected PC‐3 cells with (shPHF8) or without (EV) PHF8 knockdown into the tail vein and monitored the number and size of tumor nodules in the lungs." (PMID 33009820, 2021). "Hence, we could safely concluded that PHF8-mediated FIP200-dependent autophagy was crucial for degradation of E-cadherin, EMT and tumor metastasis, and complementary to transcriptional repression of E-cadherin by SNAI1 upregulation in HCC." (PMID 30180906, 2018). "Although PHF8 upregulated N-cadherin, a key protein to facilitate transepithelial migration of tumor cells, much more effort is still under way to enucleate the exact mechanism of this process, on account of non-involvement of PHF8 in transcriptionally activating N-cadherin expression." (PMID 30180906, 2018). "In this study we show that the microRNA hsa-miR-137 (miR137) tumor suppressor regulates expression of an extended network of transcriptional coregulators including KDM1A/LSD1/AOF1, KDM2A/JHDM1A/FBXL11, KDM4A/JMJD2A, KDM5B JARID1B/PLU1, KDM7A/JHDM1D/PHF8, MED1/TRAP220/DRIP205 and NCoA2/SRC2/TIF2." (PMID 26461474, 2015).
lip (3 papers, 2017 to 2022). "Mutations in PHF8 are associated with X-linked mental retardation and cleft lip/cleft palate, and the modulation of histone methylation by PHF8 plays a critical role in neuronal differentiation and brain and craniofacial development." (PMID 35179962, 2022).
adenocarcinoma (2 papers, 2018 to 2021). A common cancer characterized by the presence of malignant glandular cells. "We also compared the expression of 32 genes from a panel of 70 genes considered as NEPC identifiers; the results suggest that the tumors derived from Phf8‐KO cells more represent adenocarcinomas." (PMID 33009820, 2021). "In the TRAMP model system, PHF8 plays an indispensable role in NEPC development, although knocking out Phf8 has minimal effect on the development of adenocarcinoma." (PMID 33009820, 2021). "When we returned to our primary mouse adenocarcinoma data, we found that a different H3K9me1/2 demethylase, Phf8, was significantly upregulated in Sca-1+ TPCs (3.6-fold, P = 0.022, t test)." (PMID 30455465, 2018). "We found that PHF8 plays a minimum role in initiation and progression of adenocarcinoma." (PMID 33009820, 2021). "Adenocarcinoma lesions were observed in both groups at weeks 25 (n = 5) and 37 (n = 8), with a slight increase in TRAMP/Phf8‐KO." (PMID 33009820, 2021). "AR‐positive adenocarcinomas were seen in both control and Phf8 knockout TRAMP mice at week 25 (data not shown)." (PMID 33009820, 2021). "Finally, the IHC scores of the PHF8 and FOXA2 staining in 59 adenocarcinoma, 13 CRPC‐Adeno, and 10 NEPC or NED specimens indicate that expression of PHF8 and FOXA2 in NEPC tissues is much higher than in adenocarcinoma (Adeno) and CRPC‐Adeno tissues." (PMID 33009820, 2021).
infection (2 papers, 2013 to 2023). The state of being infected such as from the introduction of a foreign agent such as serum, vaccine, antigenic substance or organism. "Importantly, inflammation- and infection-related pathways and intracellular virus sensing signals were consistently activated in Phf8 knockdown CT26 tumors from immunocompetent mice." (PMID 37454216, 2023). "Using short hairpin RNA via lentiviral infection, we established stable ESCC cell lines with constitutive downregulation of PHF8 expression." (PMID 24146981, 2013).
neurodevelopmental disorder (2 papers, 2024 to 2026). A behavioral and cognitive disorder with onset during the developmental period that involves impaired or aberrant development of intellectual, motor, or social functions. "PHF8 is indispensable for developmental processes and the loss of PHF8 enzyme activity is linked to neurodevelopmental disorders." (PMID 39311138, 2024).
PHF8 also shares sentences with these, for which no sentence is quoted: acute myeloid leukemia (2 papers); autism spectrum disorder (2); bladder cancer (1); breast tumor (1); developmental delay (1); diabetes (1); esophageal cancer (1); fragile X syndrome (1); hyperhomocysteinemia (1); Kabuki syndrome 1 (1); leukemia (1); metabolic disorders (1); metastatic cancer (1); mucinous carcinoma (1); nervous system diseases (1); neuroendocrine carcinoma (1); pancreatic cancer (1); prostate (1); Skin Cutaneous Melanoma (1); Stroke (1); T-cell acute lymphoblastic leukemia (1); triple-negative breast carcinoma (1); West syndrome (1).